CD4 (CD4 molecule)
Diseases named in the same sentence as CD4 in open-access papers (continued):
Sharing a sentence is not in itself a finding about the gene and the disease.
co-infection (continued). "Therefore, the objective of this study was to investigate the expression of FOXP3+ Treg cells in leprosy skin lesions and to correlate their clinical forms, laboratory characteristics (CD4, CD8, and CV), and the immune reconstitution syndrome in HIV-leprosy co-infection." (PMID 34748560, 2021). "It has been suggested that significant baseline immune suppression, early commencement of ART and a good response to ART (evidenced by the increase in CD4 counts and suppressed HIV viral load) might be important contributory factors to the development of PR in BU-HIV coinfection." (PMID 33832460, 2021). "Third, the difference in the CD4 cell count between patients with co-infection and those with Plasmodium mono-infection could not be meta-analysed as the CD4 data reported by some included studies were insufficient." (PMID 34404814, 2021). "TB co-infection had a negative significant effect on CD4 counts (P < 0.05)." (PMID 33766121, 2021). "Therefore, in our study HIV/HCV coinfection was associated with an overall peripheral reduction—and not due to a reduction in surface expression per cell—of CCR5 expressing CD4+ and CD8+ T cells compared with HCV and HIV monoinfection." (PMID 34696504, 2021). "No obvious clustering of samples based on HIV co-infection or CD4 cell count was observed." (PMID 32750098, 2020). "Furthermore, these findings may also explain why T. gondii cysts reactivate after HIV co-infection in humans; HIV destroys CD4+ T cells, a prime IFN-γ producer." (PMID 32753607, 2020). "However, in the absence of TB co-infection, we demonstrate that widely available pre-treatment markers such as CD4+ T-lymphocyte count and percentage are strong predictors of immune recovery, offering diagnostic accuracy as high as 74%." (PMID 33059622, 2020). "CD4 T cell responses to other antigens in Mtb may have different cytokine profiles and may be more or less malleable to a TH2 stimulus such as a helminth co-infection." (PMID 32117277, 2020). "Previous studies indicate that the cytokine profile and the frequencies of M. tuberculosis-specific CD4 T cells could be impacted by HIV coinfection and that these responses were not fully restored under cART." (PMID 30541853, 2019). "A previous co-infection study conducted in the rhesus macaque model has shown that a pre-existing SFV infection can influence the biology and the outcomes of an SIV infection, including higher plasma SIV VL, a decreasing trend in the CD4+ T-cell counts and a greater number of animal deaths." (PMID 30544924, 2018). "Importantly, we found that co-infection with hepatitis B or C, level of CD4 count and use of ART did not have a significant effect on CKD prevalence." (PMID 29659605, 2018). "Interestingly high CCL2 levels have also been linked with disease severity of TB patients Innate immunity is a key signature in our cohort, with an increase in both phenotypic and functional (cytokine producing) CD4+ and CD8+ semi-invariant Vα7.2+CD161+ cells in TB/Flu co-infection." (PMID 30662443, 2018). "Our secondary goals were to compare the baseline HIV viral load and CD4 count among cases with and without HSV-2 co-infection and to investigate the association of HSV-2 serostatus with CD4 count and HIV viral load changes in naïve HIV subjects, after one year follow-up." (PMID 28688377, 2018). "The lack of the Th2 immune responses in co-infection may suggest that the CD4+ T cells are not responding to H. polygyrus infection." (PMID 28791259, 2017).
co-infection (continued). "Given that mucosal organs are a principal target for HIV-mediated CD4+ T-cell destruction, we investigated M. tuberculosis–specific responses in bronchoalveolar lavage (BAL) from persons with latent M. tuberculosis infection and untreated HIV coinfection with preserved CD4+ T-cell counts." (PMID 29029171, 2017). "Another possibility is that HIV-1 co-infection may have additional influence on the development of KS independent of its effects on suppression of CD4+ T cell immunity; several such potential mechanisms are discussed later in this review." (PMID 26913028, 2016). "Since LTBI has been associated with markers of CD4 and CD8 T-cell activation in the peripheral blood of persons with and without HIV co-infection, it is possible that these cells may be a source of IFN-γ." (PMID 27853753, 2016). "In the Italian cohort ICONA, the proportion of normalisation of CD4/CD8 ratio above 1 was 29.4% at 5 years of follow-up and an additional factor found associated with higher ratio was the lack of co-infection with cytomegalovirus (CMV), a data that was not available in our cohort." (PMID 27548257, 2016). "To address these questions, we recruited 164 HIV-1-infected individuals with different statuses of M. tb co-infection and evaluated whether hierarchy declines of CD4+ and CD8+ T-cell counts and effector functions correlated with M. tb co-infection and active TB." (PMID 26959228, 2016). "Speculatively, co-infection may drive non-protective inflammation during early stages of HIV disease while immune compromise, including loss of IFN-γ, predominates once CD4+ T cell depletion ensues." (PMID 26908312, 2016). "Effectiveness outcomes included CD4+ count, viral load, absence of co-infections and optimal immune response, and economic outcomes included expenses of physician and pharmaceutical appointments, laboratory tests, procedures, and hospitalizations, at six months and one year." (PMID 25889580, 2015). "However, the mean CD4+ T cell count in asymptomatic HIV-1 positive individuals with helminths was lower than that of those without helminth co-infection (577 ± 128 versus 635 ± 90 cells/mm3)." (PMID 26187732, 2015). "For both HIV-specific CD4+ and CD8+ T cells we observed a decline in polyfunctional capacity in MTB co-infection suggesting that mycobacterial load may a role.This is supported by lower MTB-specific T cell functionality in TB co-infection with HIV compared to LTBI." (PMID 25781898, 2015). "Independent of HIV co-infection, IFNγ+ CMVpp65-specific CD4+ T cell frequencies increased with age." (PMID 25974183, 2015). "An additional health care system daily investment of US$1.45, 1.09, 2.13, 4.35, 1.09, and 0.87 would be required for each additional outcome of viral load <50 copies/ml, absence of co-infection, CD4+ >200, 350, and 500 cells/mm3, and optimal immune response, respectively." (PMID 25889580, 2015). "Hundreds of thousands of people in Cameroon are infected with HIV with an estimated prevalence of 4.3% in calendar year 2011 but little data are available on their HBV/HCV co-infection status despite recommendations from the WHO that these patients be placed on ART irrespective of their CD4 count." (PMID 26371878, 2015). "However, significantly lower CD8+ T cell counts (858/μL vs. 990/μL, p = 0.02), and a trend towards higher CD4/CD8 ratios (0.55 vs. 0.49, p = 0.07), as possible indicator of decreased immune activation, were noted among those patients with H. pylori co-infection." (PMID 26599971, 2015). "This HIV positive participant with low CD4 counts could have been missed by both tissue MTB culture and histopathology due to low mycobactereology load and inability to form granulomas respectively, as commonly found in HIV/TB co infection." (PMID 25051491, 2014).
co-infection (continued). "Given the impact of both HIV-1 and T. vaginalis on immune activation locally and systemically, it can be hypothesized that coinfection alters immune responses and may alter either CD4 cell count or HIV-1 viral load, but there are no data to support this." (PMID 26316953, 2013). "However, co-infection of individual cells would not explain the global reduction in CD4+ T cell activation and proliferation that we observed." (PMID 23209780, 2012). "Co-infection with HIV alters the natural history of chronic hepatitis B. Increasing serum HBV DNA concentrations, decline in liver enzyme levels and developing faster liver cirrhosis, particularly in those with low CD4 counts, are some of the symptoms of this phenomenon." (PMID 22737429, 2011). "Indeed, HBV-specific CD4+ lymphocyte activity has been shown to be important for control of HBV infection in those without HIV coinfection as well." (PMID 21991507, 2011). "Although individuals are at a high risk of developing TB within the first year of HIV-seroconversion, clinical studies of HIV-Mtb co-infection indicate that depletion of peripheral CD4 T cell numbers is not predictive of when individuals are most likely to experience TB." (PMID 20224771, 2010). "Moreover, CD4+ T Lymphocytes from co-infected patients presented significantly higher levels of CD45RO and CD25, but lower levels of CD45RA and CD62L, strongly indicating that CD4+ T cells are more activated under HTLV-1 plus HIV co-infection." (PMID 20028500, 2009). "Activation of parasite-specific CD4+ T cells, especially the CCR5+ CD4+ T cells, in response to parasitemia could be driving the higher viral loads as has been observed in HIV/Plasmodium co-infections." (PMID 19774084, 2009). "Interestingly, in our study cohort, HIV viral load and HCV co-infection were not significantly related to healthcare utilization outcomes, and patients with lipodystrophy demonstrated higher CD4 counts and lower viral loads than comparison counterparts." (PMID 18593479, 2008). "The manner by which HSV-2 co-infection may confer a protective effect on CD4+ T cell populations is not clear." (PMID 17957262, 2007). "Similarly, a significantly higher percentage of SARS-CoV-2-specific IFN-γ positive CD4+ T cells was also observed in the SARS-CoV-2 single infection group (0.66 ± 0.01%) than in the IAV + SARS-CoV-2 (0.44 ± 0.01%, P < 0.001) and SARS-CoV-2 + IAV (0.30 ± 0.06, P < 0.0001) coinfection groups." (PMID 35107382, 2022). "In light of the ‘test and treat’ strategy in Kenya, initiation of ART is no longer based on CD4 count but it is important to know the RIs as this may influence prognosis and treatment response and is used to determine the timing of co-infection prophylaxis initiation." (PMID 33784358, 2021). "In addition, we could not exclude the negative impact of defective particles in HIV/HTLV-1 coinfection, since low CD4+ cell counts, high HIV viral load levels, and more X4 HIV strains were detected in such patients." (PMID 32999083, 2020). "Therefore, we could not explore the impact of CMV coinfection on the correlation between CD4:CD8 ratio and such events." (PMID 27824907, 2016). "However, in persons with HIV/TB co-infection, treatment of TB has not impacted CD4 counts." (PMID 20179751, 2010). "While other clinical variables—including CD4/CD8 ratios, nadir CD4 counts, and HCV co-infection—did not correlate with neutralization capacity, HTLV-2 co-infection remained a significant determinant." (PMID 40573970, 2025). "At the outset, PLHIV with LTBI (HLTBI+ group) exhibited a disease progression profile comprising the highest CD4+ T-cell counts and CD4/CD8 ratios and viremia similar to the group without co-infection (HLTBI−)." (PMID 41148837, 2025). "In an analysis of the leprosy and HIV co-infection group, it was found that, regardless of the clinical form, the majority were using HAART at the time of diagnosis and had a CD4+ T lymphocyte count of less than 350 cells per cubic millimeter." (PMID 41156731, 2025).
co-infection (continued). "After co-infection, NHPs also display AIDS-like features as in humans, such as massive reduction of CD4+ T cells and a high viral load in the sera without anti-retroviral treatment, as well as chronic immune activation in animals during extended observation." (PMID 38799434, 2024). "TB/HIV co-infected patients who visited city-level health facilities, were severely ill, had both PTB and EPTB coinfection, did not receive ART, and with a baseline CD4+T-lymphocyte count <200 cells/μL had the highest mortality rate." (PMID 36749231, 2023). "This study showed that co‐infections of T. gondii, HCV, and HBV had a negative correlation with CD4 counts of the patients." (PMID 36840494, 2023). "Our study showed that co‐infections of T. gondii, HCV, and HBV were common among HIV‐infected patients and co‐infections had a negative correlation with CD4 + cell counts of the patients." (PMID 36840494, 2023). "In Exp 2, H3N2-specific CD4+ and CD8β+ T-cell responses in BALCs were also higher but not significantly so after PRRSV-2/H3N2 co-infection (mean of 1.71% vs. 0.90% within CD4+ T cells and 0.54% vs. 0.36% within CD8β+ T cells)." (PMID 37287962, 2023). "Together these data suggest that the pre-existing pulmonary Mtb-specific CD4+ and CD8+ T cell responses are not negatively impacted over the course of 4 weeks following SCV2 co-infection." (PMID 37720210, 2023). "Among those with no available CD4 data, the percentages without data on HBV and HCV co‐infections were higher." (PMID 37221951, 2023). "Our present study also revealed a negative correlation between HCV infection and optimal CD4 + T cell recovery, suggesting that all patients with HCV/HIV coinfection should be evaluated for curative HCV treatment." (PMID 35135485, 2022). "Lower CD4+ cells/μL and higher viral load/μL were found among CDR patients in comparison to non-reactivation group at the co-infection diagnosis." (PMID 34591866, 2021). "The years 2014/201548 were the first following implementation of other eligibility criteria that defined co-infection with TB, Hepatitis B, cancer, and HTLV as criteria for starting ART, regardless of WHO stage or CD4 cell count." (PMID 34504234, 2021). "In this study, we assess the ability of pre-HAART CD4+ T-lymphocyte counts and percentages to be used as biomarkers of post-HAART immune recovery in HIV-infected children with and without TB co-infection." (PMID 33059622, 2020). "The frequency of these receptors on CD4 T cells was not significantly different when the data was further stratified into different permutations of HIV and HPV co-infections." (PMID 33007050, 2020). "According to previous reports, 60–70% of VL cases with HIV co-infection and on ART relapse within one year in the absence of secondary prophylaxis, the relapse rate being higher with a lower CD4 count." (PMID 30789910, 2019). "Closer monitoring of the evolution of CD4, cytokine profile, and HIV viral load would have allowed for a better understanding of the pathophysiology of co-infection, but this was not possible in the clinical settings where the trial was conducted." (PMID 30653490, 2019). "Together, these results show that CXCR3 and not CCR5, is functionally important for CD4+ T-cell migration during CHIKV infection, and co-infection sufficiently abrogates CXCR3-mediated joint swelling." (PMID 30254309, 2018). "It is important to note that most of the biomarkers used in the algorithm in HIV/HCV co-infection, with the exception of one (22.8-k(m/z)), did not correlate with markers of HIV disease progression (e.g. HIV RNA or CD4 counts)." (PMID 29608613, 2018). "Conversely, HBV coinfection does not substantially influence the progression of HIV infection and suppression or the CD4 cell response following cART24." (PMID 28951598, 2017). "To identify the changes induced by HIV co-infection we compared MTB-specific CD4+ responses in subjects with active TB and latent TB infection (LTBI), with and without HIV co-infection." (PMID 26756579, 2016).
co-infection (continued). "Age, route of HIV infection, baseline CD4 count, baseline HIV RNA, ART regimen, prior ART and HIV-1 subtype, but not HBV or HCV co-infection, affected HIV RNA suppression." (PMID 26933963, 2016). "Taken together, we found that HIV infection contributes to progressive liver disease in the context of HCV co-infection, most likely by modulating HCV specific T cell responses in particular CD4+ T cells but not HCV specific neutralizing antibody responses." (PMID 27455208, 2016). "tb co-infection and hierarchy declines of CD8+/CD4+ T-cell counts and IFN-γ responses have not been done." (PMID 26959228, 2016). "The frequency of MTB-specific CD4+ tri-functional T-cells secreting IFN-γ, IL-2 and TNF-α was independent of both mycobacterial burden and HIV co-infection." (PMID 26756579, 2016). "In HIV co-infection CD127 was relatively less frequently expressed on MTB-and CMV-specific IFN-γ and IL-2-dual-secreting cells compared with EBV-specific CD4+ cells than in those without evidence of HIV infection." (PMID 26417433, 2015). "Across most subsets especially those secreting IFN-γ, EBV-specific CD4+ cells more frequently expressed PD-1 than MTB-specific CD4+ cells in those with and without evidence of HIV co-infection for example IFN-γ-only secreting cells." (PMID 26417433, 2015). "There was a significantly higher frequency of CD25+FoxP3+ CD4 T-cells in PTB infected individuals with (mean±SEM: 8.57±1.07, p = 0.0012) and without (mean±SEM: 6.09±0.39, p = 0.035) HIV-1 co-infection when compared to healthy controls (mean±SEM: 5.04±0.33)." (PMID 25198707, 2014). "It is now rapidly scaling up its treatment programme aiming to cover all HIV-infected people with a CD4 cell count of ≤350 μl patients with a TB co-infection, and HIV-infected pregnant women irrespective of CD4 cell count." (PMID 24107435, 2013). "Our study design has allowed us to correlate clinical variables with CD4 cell counts longtitudinally during ATT in patients with TB, both with and without HIV co-infection." (PMID 24358268, 2013). "HIV-HBV co-infection did not significantly impact on other baseline characteristics including, gender, WHO clinical stage, median absolute CD4 count, mean viral load, median ALT, and hepatotoxicity." (PMID 23691352, 2013). "CD4 counts were assessed from time of diagnosis till the end of TB treatment in a cohort of pulmonary TB patients with and without HIV co-infection and compared with cross-sectional data on age- and sex-matched non-TB controls from the same area." (PMID 22436147, 2012). "Our study shows that high ferritin levels are strongly (and inversely) related to CD4 cell numbers but not to gender, HCV co-infection nor CRP as a marker of inflammation, as has been suggested by others." (PMID 21827653, 2011). "Factors associated with higher mortality included non-active duty status, lower CD4 count at HAART initiation, higher VL at HAART initiation, HCV co-infection, and lower Hgb." (PMID 20507622, 2010). "Moreover, determinants of mortality were also reported include low CD4 cell count, advanced HIV disease, lack of antiretroviral therapy (ART), TB drug resistance, disseminated TB, and other opportunistic co-infections." (PMID 39095740, 2024). "After excluding those with <365 days of observation after the qualifying HBV laboratory test (n = 210) or no available HIV RNA and CD4+ cell measurements during the observation period (n = 1,295), 3,953 people with HIV/HBV coinfection remained in the final sample." (PMID 37656704, 2023). "The higher incidence of BC observed in some sub-populations of WLWH may be explained, at least partially, by the HIV-related characteristics (nadir CD4 > 200 cells/mm3, HIV transmission through IVDU, HIV diagnosis before 2000) and absence of HCV coinfection." (PMID 35333883, 2022).